CBY2 (chibby family member 2)
Synonyms: SPERT; NURIT
Tractability: No criterion of Open Targets' tractability assessment is met for any kind of drug.
Gene: Protein-coding gene on chromosome 13 (45,702,320 to 45,714,559, forward strand). Ensembl gene ENSG00000174015.
Subcellular location (Human Protein Atlas): Annulus; Calyx; Connecting piece; End piece; Mid piece; Principal piece
Gene Ontology:
Molecular function: protein binding
Cellular component: cytoplasmic vesicle
Genetic constraint (gnomAD): Loss-of-function variants: 27 observed, 26.73 expected, observed/expected ratio (o/e) 1.01, 90% interval 0.74 to 1.39. The upper end of that interval is the gene's LOEUF score, 1.39, which puts it in group 5 of 6, group 1 being the genes least tolerant of losing a copy. Missense variants: 640 observed, 571.21 expected, observed/expected ratio (o/e) 1.12, 90% interval 1.05 to 1.2. Synonymous variants: 278 observed, 246.3 expected, observed/expected ratio (o/e) 1.13, 90% interval 1.02 to 1.25.
Homologues: Orthologues: chimpanzee CBY2 (98% identical), macaque CBY2 (96% identical), rabbit CBY2 (80% identical), rat Cby2 (79% identical), mouse Cby2 (79% identical), dog CBY2 (77% identical), guinea pig CBY2 (76% identical), pig CBY2 (75% identical). Paralogues in human: CBY3 (13% identical), CCDC70 (12% identical), CBY1 (8% identical).
Diseases named in the same sentence as CBY2 in open-access papers:
CBY2 is named in the same sentence as 1 disease in open-access papers, as found by Europe PMC text mining. Sharing a sentence is not in itself a finding about the gene and the disease.
CBY2 shares sentences with these, for which no sentence is quoted: tumor (1 paper).